BECN1 (beclin 1)
Diseases named in the same sentence as BECN1 in open-access papers (continued):
Sharing a sentence is not in itself a finding about the gene and the disease.
ovarian carcinoma (continued). "More recently, studies in an ovarian cancer cell line showed that ectopic expression of Ras induces autophagic cell death through the upregulation of Beclin-1 and Noxa, a BH3-only protein, which ultimately limits the oncogenic potential of Ras." (PMID 25328887, 2014). "In this study, we investigated the relationship between the level of Beclin 1 expression and prognosis in ovarian cancer." (PMID 24675697, 2014). "Next, we looked for any correlation between the extent of BECLIN 1 expression and the aggressiveness of ovarian cancers as mirrored by the histologic grading and the pathological stage at diagnosis." (PMID 25136588, 2014). "We used immunoblotting to detect the expression of Beclin 1 at the protein level and found that the levels of Beclin 1 were higher in the ovarian carcinoma than in the normal ovarian tissues." (PMID 24675697, 2014). "The relationships between Beclin 1 protein expression and ovarian cancer pathological characteristics were analyzed." (PMID 24675697, 2014). "In the present study, Beclin 1 expression correlated positively with ovarian cancer differentiation in Asian patients (p < 0.05), suggesting that Beclin 1 is a protective factor in ovarian cancer." (PMID 24675697, 2014). "Beclin 1 protein is upregulated in ovarian epithelial cancer and is a prognostic factor for this cancer." (PMID 24675697, 2014). "The rate of high Beclin 1 expression differed significantly between patients with well-moderately differentiated ovarian cancers (69.1%) and those with poorly differentiated cancers (51.9%; p < 0.05)." (PMID 24675697, 2014). "Beclin 1 protein is upregulated in ovarian epithelial cancer and is a prognostic factor of ovarian cancer." (PMID 24675697, 2014). "The positive rates of Beclin 1 were significantly higher in ovarian epithelial cancer and borderline tumor than in benign ovarian tumor or normal ovarian tissue (all p < 0.001)." (PMID 24675697, 2014). "We investigated the expression of Beclin 1 protein in ovarian epithelial tissues and correlated it with the prognosis of ovarian cancer." (PMID 24675697, 2014). "Beclin 1 protein expression was determined using immunohistochemistry in 148 patients with ovarian epithelial cancer, 26 with ovarian borderline tumor, 25 with benign ovarian tumor, and 30 with normal ovarian tissue." (PMID 24675697, 2014). "A survival curve was plotted from the follow-up data of 93 patients with ovarian cancer to analyze the effects of Beclin 1 expression on the prognosis of ovarian cancer." (PMID 24675697, 2014). "The positive expression rate of Beclin 1 was 80.41% in ovarian epithelial cancers, 73.08% in borderline tumors, 23.08% in benign tumors, and 20.00% in normal ovarian tissues." (PMID 24675697, 2014). "Further correlation analyses evaluated that low expression of Beclin 1 in our ovarian carcinoma cohort was positively correlated with an ascending histological grade, late pT stage, lymph node metastasis, distant metastasis and/or advanced FIGO stage." (PMID 23573264, 2013). "Further correlation analysis demonstrated that Beclin 1 expression was significantly inversely correlated with Bcl-xL expression in our ovarian carcinoma cohort." (PMID 23573264, 2013). "Further correlation analysis showed a significant inverse correlation between Beclin 1 and Bcl-xL expressions in our ovarian carcinoma cohort (P = 0.001, Fishers exact test)." (PMID 23573264, 2013). "An apparent decrease in protein expression of Beclin 1 was detected in ovarian carcinoma tissues compared to adjacent ovarian tissues." (PMID 23573264, 2013). "In this study, decreased expression of Beclin 1 was examined in 94/169 (55.6%) of ovarian carcinomas." (PMID 23573264, 2013). "Decreased expression of Beclin 1 was examined by IHC in 8.3% of normal ovaries, in 15.4% of cystadenomas, in 20.0% of borderline tumors, and in 55.6% of ovarian carcinomas, respectively." (PMID 23573264, 2013).
ovarian carcinoma (continued). "To determine if altered expression of Bcl-xL influences the Beclin 1-related prognosis, we evaluated the ovarian carcinoma patients' survival after stratification by Bcl-xL expression." (PMID 23573264, 2013). "When all cases of ovarian carcinoma were stratified by Bcl-xL expression, we found that the prognosis of patients with low Beclin 1 expression was significantly poorer than that with high Beclin 1 expression in the Bcl-xL+ group (P<0.0001)." (PMID 23573264, 2013). "When further analyzed in Bcl-xL+ group, Beclin 1 was evaluated as well an encouraging prognostic predictor for ovarian carcinoma patients survival (AUC = 0.675, P<0.0001)." (PMID 23573264, 2013). "In ovarian carcinomas, decreased expression of Beclin 1 was correlated closely with ascending histological grade, later pT/pN/pM status and/or advanced clinical stage (P<0.05)." (PMID 23573264, 2013). "In this study, the protein expression of Beclin 1 was first examined by Western blotting in 5 pairs of primary ovarian carcinoma and adjacent normal ovarian tissues." (PMID 23573264, 2013). "The increasing frequency of decreased expression of Beclin 1 in normal ovarian tissues (8.3%), benign cystadenomas (15.4%), borderline tumors (20.0%), and ovarian carcinomas (55.6%) was statistically significant (P<0.0001)." (PMID 23573264, 2013). "In this study, we evaluated that decreased expression of Beclin 1 in ovarian carcinoma was as well a strong and independent predictor of short patient survival." (PMID 23573264, 2013). "Western blotting assay revealed that down-regulation of Beclin 1 was detected in ovarian carcinoma tissues, when compared with their adjacent normal ovarian tissues." (PMID 23573264, 2013). "Collectively, these data suggested that Beclin 1 sensitized ovarian cancer cells to proteasome inhibitors in an autophagy-independent manner." (PMID 23270461, 2012). "Recently it has been reported that arsenic trioxide induces a Beclin-1-independent autophagic cell death in ovarian cancer cells." (PMID 21912568, 2012). "Overexpression of Beclin 1 significantly enhanced proteasome inhibitors-induced cytotoxicity of ovarian cancer cells, as assessed by cleavage of PARP, MTT assay, nuclei staining with Hoechst 33258, and caspase 3 activity assay." (PMID 23270461, 2012). "Accordingly, the expression of beclin 1 was found down-regulated in ovarian cancers, compared to benign lesions." (PMID 22974323, 2012). "For the first time, the current study demonstrated that proteasome inhibitors induced PI3K and Beclin 1-independent autophagy in ovarian cancer cells." (PMID 23270461, 2012). "BECN1 is a key component of the PI3K complex, and the deletion of BECN1 gene has been found to be closely associated with the development of breast, prostate, and ovarian cancer." (PMID 40231206, 2025). "A reduced expression of PTEN and Beclin-1 has been observed in chemoresistant ovarian cancers." (PMID 39273093, 2024). "Deletion of Beclin 1 has been observed in various human breast, prostate, and ovarian cancers." (PMID 39349421, 2024). "Thr119 and Ser93 phosphorylation of BECN1 may be used as a predictive marker for poor prognosis in ovarian cancer, as well as a marker for the potential benefit of ovarian cancer drug therapy and early identification of drug resistance." (PMID 39695078, 2024). "It is suggested that LOC730101 may play a role in promoting drug sensitivity in ovarian cancer cells by specifically binding to the autophagy key protein BECN1." (PMID 39695078, 2024). "Moreover, TXNDC17 promotes tumor resistance to paclitaxel in ovarian cancer by regulating BECN1‐mediated autophagy, and high TXNDC17 expression has been confirmed to be associated with poor prognosis in patients with ovarian cancer." (PMID 39411839, 2024).
ovarian carcinoma (continued). "Knocking down BECN1 and microtubule-associated protein 1 light chain 3 beta (MAP1LC3B/LC3B), two frequently deleted autophagy genes in ovarian cancer, led to genomic instability and increased migration rates in atypical ovarian cancer cells." (PMID 38398197, 2024). "Mechanistically, LOC730101 specifically binds to BECN1 and inhibits the formation of autophagosome BECN1/VPS34 by reducing phosphorylation of BECN1, thereby inhibiting autophagy and promoting drug sensitivity in ovarian cancer cells following treatment with cisplatin and PARP inhibitors." (PMID 39695078, 2024). "We therefore hypothesized that LOC730101 might play a role in promoting drug sensitivity in ovarian cancer cells through the regulation of autophagy and apoptosis by BECN1." (PMID 39695078, 2024). "BECN1 gene deletion is observed in 40%–75% of ovarian cancers." (PMID 36760166, 2023). "Beclin-1 protein expression was shown necessary to block the apoptotic cascade after induced-DNA damage and to activate autophagy under low doses of chemotherapeutics (rapamycin, tamoxifen) in breast and ovarian cancers." (PMID 35280788, 2022). "Interestingly, patients with ovarian cancer presenting co-deletions of BECN1 and BRCA1 were found to benefit from platinum-based therapy and show improved chances of survival." (PMID 36008963, 2022). "Depletion of the BECN1 is also observed in human breast, prostate, and ovarian cancers." (PMID 35211417, 2022). "In fact, the ovarian cancer cell line OVCAR-3 with monoallelic losses of BECN1 and LC3 is more sensitive to various autophagy-stressing drugs than the SKOV-3 ovarian cancer cell line without these deletions, while the latter is sensitized by the RNAi knockdown of either BECN1 or LC3." (PMID 35681458, 2022). "We observed that the vast majority of the tumors at stage III and IV and of grade 3 were bearing shallow deletions (i.e., expressing one single allele) of both BECN1 and BRCA1, further indicating that the low expression of these tumor suppressor genes associates with ovarian cancer progression." (PMID 33670664, 2021). "Particularly, reduced expression of PTEN and BECLIN 1 was revealed in ovarian cancer tissues." (PMID 32708484, 2020). "Becn1 expression loss was demonstrated to act as a negative prognosticator in ovarian cancer patients receiving platinum-based chemotherapy." (PMID 33425768, 2020). "In drug-resistant ovarian cancer PTEN may cooperate with BECLIN 1, to block signaling inducing macrophage activity modification." (PMID 32708484, 2020). "In addition, PD-L1 promotes the autophagy of ovarian cancer cells by up-regulating the expression of BECN1, a crucial molecule involved in the regulation of autophagy." (PMID 31799599, 2019). "We hypothesized that DIRAS3 first binds BECN1 through its switch II region, and that inhibiting this interaction with a DIRAS3-derived peptide capable of binding Beclin1, would decrease autophagy and possibly inhibit dormant ovarian cancer cells." (PMID 31003488, 2019). "Arsenic trioxide also induced Beclin 1-independent autophagic pathway in ovarian cancer cells." (PMID 28545442, 2017). "Although beyond the scope of this study, it will be important to determine whether expression of HMGB1 in ovarian cancer is associated with other markers of autophagy including LC3B and Beclin-1." (PMID 29254158, 2017). "Furthermore, high Beclin-1 expression has been shown to be a poor prognostic factor in ovarian cancer, nasopharyngeal carcinoma, but a favorable prognostic factor in GC, intrahepatic cholangiocarcinoma, hepatocellular carcinoma and colorectal cancer." (PMID 28070138, 2016).
ovarian carcinoma (continued). "Therefore, our findings in iOvCa147-E2 and HeyA8 cells demonstrate the dispensability of Beclin-1 for autophagy induction, yet suggest a possible role for this this protein in contributing to ovarian cancer cell viability." (PMID 26239434, 2015). "Our study, however, represents the first effort to systematically address Beclin-1-independence in early-passage, ascites-derived ovarian cancer cells as well as established ovarian cancer lines selected for their differing BECN1 gene copy-number as well as mRNA and protein expression." (PMID 26239434, 2015). "BECN1 has therefore been identified as a candidate tumor suppressor gene for ovarian cancer." (PMID 25789037, 2015). "Decreased expression of Beclin-1 has been found to be inversely correlatedwith altered expression of Bcl-xL in ovarian carcinoma,and its expression has thus been used topredict patient survival in ovarian carcinomas withincreased expression of Bcl-xL." (PMID 25780525, 2015). "Therefore, it was concluded that the occurrence of drug resistance in ovarian cancers was closely associated with a low expression of PTEN and Beclin-1." (PMID 25789037, 2015). "Conversely, an upregulation in the expression of the Beclin-1 protein may increase the sensitivity of ovarian cancers to chemotherapy, which could improve treatment efficiency and prognoses." (PMID 25789037, 2015). "Thus, representative ovarian cancer cell lines of low, intermediate, and high endogenous Beclin-1 expression are able to robustly induce autophagy." (PMID 26239434, 2015). "In summary, the protein expression of Beclin-1 and PTEN was downregulated, which suggested that a decrease in autophagic activity may be associated with drug-resistant ovarian cancers." (PMID 25789037, 2015). "BECN1 copy-number and mRNA expression level were plotted for 51 ovarian cancer cell lines." (PMID 26239434, 2015). "We sought to clarify whether Beclin-1 expression is in fact disrupted in ovarian cancer and whether this impacts autophagy regulation." (PMID 26239434, 2015). "In this study, using large samples of tissues from the northeast of China, we found that the positive expression rate of Beclin 1 in ovarian epithelial cancers (80.41%) was significantly higher than that in benign ovarian tumors (23.08%) or normal ovarian tissues (20.00%) (all p < 0.001)." (PMID 24675697, 2014). "Also, miR-30a, which negatively regulates the expression of Beclin-1 in ovarian cancer cells, was found deregulated in stage I ovarian cancer patients together with other miRNAs; in particular, it was downregulated in samples from relapsing patients." (PMID 24877083, 2014). "However, the prognostic significance of BECLIN 1 expression in ovarian carcinomas appears controversial." (PMID 25136588, 2014). "In summary, Beclin 1 protein is overexpressed in ovarian cancer and may play an important role in the development of this malignancy." (PMID 24675697, 2014). "This could also explain the poor survival reported in women bearing an ovarian cancer expressing low level of BECLIN 1 and high level of BCL-xL." (PMID 25136588, 2014). "Of these, as many as 24 (75%) were bearing an ovary cancer with ≥20% BECLIN 1-positive cells." (PMID 25136588, 2014). "It has been suggested that autophagy-related Beclin 1 plays a critical role in the regulation of tumor development and/or progression, but its prognostic significance and relationship with Bcl-xL expression in ovarian carcinoma are unclear." (PMID 23573264, 2013). "Our results provide a basis for the concept that decreased expression of Beclin 1 may represent an acquired malignant phenotypic feature of ovarian carcinoma cells." (PMID 23573264, 2013). "In univariate survival analysis, a highly significant association between low-expressed Beclin 1 and shortened patient survival was evaluated in ovarian carcinoma patients (P<0.01), and Beclin 1 expression was an independent prognostic factor as evidenced by multivariate analysis (P = 0.013)." (PMID 23573264, 2013).
ovarian carcinoma (continued). "In addition, decreased expression of Beclin 1 was inversely correlated with altered expression of Bcl-xL in ovarian carcinoma cohort, and combined analysis further showed that the low Beclin 1/high Bcl-xL group had the lowest survival rate." (PMID 23573264, 2013). "Thus, Beclin 1 expression appears to have the potential to predict ovarian carcinoma patient clinical outcome." (PMID 23573264, 2013). "We found that low expression of Beclin 1 was, as well, closely associated with poor prognosis of ovarian carcinoma in the Bcl-xL+ group, but not in the Bcl-xL− group." (PMID 23573264, 2013). "Thus, in this study, the expression dynamics of Bcl-xL and its correlation with Beclin 1 in ovarian carcinomas were subsequently investigated." (PMID 23573264, 2013). "In addition, this study revealed autophagy-independent tumor suppressive effects of Beclin 1 in ovarian cancer cells." (PMID 23270461, 2012). "On the contrary, Beclin 1 overexpression enhanced responsiveness of ovarian cancer cells to proteasome inhibitors-mediated cytotoxicity, indicating that Beclin 1 exerts autophagy-independent tumor suppressive effect in ovarian cancer cells upon exposure to proteasome inhibitors." (PMID 23270461, 2012). "In addition, Beclin 1 sensitizes ovarian cancer cells to proteasome inhibition in autophagy-independent manner." (PMID 23270461, 2012). "Beclin 1 expression vectors or shRNA against Beclin 1 (shBeclin 1) were transfected to investigate the role of Beclin 1 in autophagy activation and cytotoxicity of ovarian cancer cells induced by proteasome inhibitors." (PMID 23270461, 2012). "Of note, monoallelic deletion of BECLIN 1 is found in more than 50% of sporadic ovarian cancers." (PMID 22974323, 2012). "Furthermore, we demonstrated that Beclin 1 overexpression enhanced proteasome inhibitors-mediated cell death of ovarian cancer cells." (PMID 23270461, 2012). "Proteasome inhibitors elicit PI3KC3 and Beclin 1 independent autophagy in ovarian cancer cells." (PMID 23270461, 2012). "Moreover, Beclin 1 overexpression enhanced anti-proliferative effects of proteasome inhibitors in ovarian cancer cells." (PMID 23270461, 2012). "Therefore, USP13-mediated Beclin-1 stabilization could promote autophagy of ovarian cancer under metabolic stress conditions, and it could be one of the possible mechanisms for the enhanced ovarian tumor metastasis in PTU mice." (PMID 35173307, 2022). "However, it may not be a unique finding of As4O6-induced autophagy because it recently has been reported that arsenic trioxide also induces a Beclin-1-independent autophagic cell death in ovarian cancer cells." (PMID 28355296, 2017). "However, whether the level is high or low in ovarian cancer is controversial, and the relationship between Beclin 1 expression and its prognosis is still unclear." (PMID 24675697, 2014). "Consistent with our hypothesis, it was recently shown that the Src/Abl kinases inhibitor Dasatinib arrested the growth of ovarian cancer xenograft by inducing BECLIN 1-dependent autophagic cell death, and hyperstimulation of autophagy was associated with downregulation of BCL-2 expression." (PMID 25136588, 2014). "Besides, the high expression of BECLIN 1 could enhance the cytotoxic response to a chemotherapeutic drug in ovarian cancer cells also via an autophagy-independent mechanism." (PMID 25136588, 2014). "A survival analysis showed that patients with high Beclin 1 expression survived significantly longer than those with low Beclin 1 expression, suggesting that the BECN1 gene might be a tumor suppressor gene and that Beclin 1 levels are associated with the prognosis of ovarian cancer." (PMID 24675697, 2014).